IL6 (interleukin 6)
Diseases named in the same sentence as IL6 in open-access papers (continued):
Sharing a sentence is not in itself a finding about the gene and the disease.
cancer (continued). "The crosstalk between cancer cells and fat tissue induces a phenotypic switch, forcing the adipocytes to produce matrix metalloproteases (e.g., MMP11) and pro-inflammatory cytokines such as IL-6, IL1β, and IL-8." (PMID 33026575, 2021). "To check whether the cancer microenvironment harbored factors that could influence Th17 subpopulations, we evaluated the mRNA levels of CD70 (the CD27 ligand), IL‐6, and TGF‐β1 in the lysates of cancer nodules and spleens." (PMID 34570961, 2021). "In pancreatic cancer, IL-6 induces the STAT3 signaling pathway and thus cancer cell proliferation." (PMID 34535145, 2021). "EBF1 inhibits IL-6 expression leading to the inhibitions of Jak-STAT, RAS and MAPK signaling pathways as well as COX-2 and MMP-9 expressions resulting in the inhibition of cancer progression." (PMID 33854627, 2021). "The results of our study indicate that IL-6/STAT3 signaling induces and promotes cancer metastasis." (PMID 33500736, 2021). "In the context of the cancer-immunity cycle, soluble signals such as cytokines represent signal 3 to balance TCR signaling either to a potent immune response (IL-2, IL-17) or a tolerogenic state (IL-10, IL-6)." (PMID 33466674, 2021). "IL-6 level was decreased in co-culture of A549 cancer cells and THP-1 macrophages with Rab37 knocked down, suggesting that Rab37-mediated IL-6 secretion in macrophage cells plays an important role in cross-talk between cancer cells, macrophages and T cells (Bar 7)." (PMID 34093869, 2021). "Both IL-6 and IL-8 can induce chemotactic activities and direct neutrophils and monocytes to inflammatory tissues, and both the IL-6/STAT3 and IL-8/STAT3 axes mediate malignancies, cancer stemness, and immune suppression." (PMID 34063134, 2021). "Moreover, the expressions of IL-1α, SRY, Oct4, IL-6, and TGF-β in BMSCs were markedly increased by cancer cell-derived EVs." (PMID 34746322, 2021). "To confirm the potential involvement of STING signaling in this rapid IL-6 production upon DNA damage, we selected a subset of five cancer cell lines from this panel to which we had access (BT-549, HS-578T, MDA-MB-231, PC-3 and SK-OV-3 cells), that exhibited various profiles of IL-6/ISGs responses." (PMID 35087822, 2021). "It remains possible, however, that CPT-driven IL-6 production in select cancer cells is independent of STING, and reliant on alternative pathways involving other innate immune sensors detecting DNA damage from the nucleus or the mitochondria." (PMID 35087822, 2021). "Given that the expression of genes such as IL-1β, IL-6, and COX-2 is nuclear factor-κB (NF-κB) dependent, we hypothesize that in poorly invasive cancer cells, the heat is an inhibitor of NF-κB, which acts in a dose-dependent manner." (PMID 34201348, 2021). "The IL-6/JAK/STAT3 pathway is important to the growth and advancement of many human cancers." (PMID 34552929, 2021). "The types of immune cells associated with TME are mostly associated with cytokine production, broadly classified as anti-tumorigenic (IL-12, IFN-γ, TRAIL), pro-tumorigenic (IL-6, IL-23, IL-10, IL-17), and cytokines with direct roles on cancer cells’ signaling (TGF-β, TNFα, IL-6, FasL)." (PMID 33390169, 2021). "Our results collectively support a direct role for STING signaling in the frequent IL-6 production in response to genotoxic treatment of cancer cells, most often independent of a marked IRF3 signature." (PMID 35087822, 2021). "Even better than IL-6, TNF-α is a key inflammatory cytokine in cancer cachexia." (PMID 34262449, 2021). "IL‐6/STAT3 signalling upregulates the expression of genes involved with cell proliferation (c‐Myc and cyclin D1), angiogenesis (VEGF) and the inhibition of apoptosis (Bcl‐xL and survivin) in cancers." (PMID 33382511, 2021).
cancer (continued). "Therefore, the IL-6/STAT3 pathway is a pharmacological target for treating human diseases, cancer included." (PMID 33806019, 2021). "The IL-6 rs1800796 mutant were related to no family history of cancer and the recessive model were significantly related to stage III-IV disease." (PMID 34150619, 2021). "Since adipocytes from obese individuals express higher levels of inflammatory cytokines, such as IL6 and TNFα, it is possible that obese adipocytes are already more “CAA-like” and more supportive of cancer cells, even before complete trans-differentiation into a distinct CAA phenotype." (PMID 33968771, 2021). "Among non-cancer participants, both IL-6 and fat mass were negative determinants of circulating omentin-1 levels." (PMID 34827610, 2021). "IL-6 cooperates with TNF-α also in stimulating the Janus kinase (JAK)-signal transducer and activator of transcription (STAT), the JAK2/STAT3 pathway, which is involved in inflammation, cancer progression, muscle mass wasting, and cancer-related cachexia." (PMID 34684523, 2021). "It is becoming evident that there is a role for interleukin-6 in inflammation and carcinogenesis, through its downstream transcription factors, such as signal transducer and transcription 3 (STAT3), which stimulates cancer cell proliferation and migration." (PMID 33923292, 2021). "The antitumor efficacy of siltuximab, a chimeric mouse-human antibody against IL-6, against multiple cancers was demonstrated; however, this effect was absent in advanced cancers 39-41." (PMID 33500736, 2021). "These correlations were independent of human HCC stage, suggesting that the downregulation of SPTBN1 and the upregulation of IL-1α, IL-1β and IL-6 occur in HCC throughout all stages of cancer progression, and also irrespective of human hepatitis virus status." (PMID 33754058, 2021). "In addition, IL-6 treatment induced IGF-1 secretion and IGF-1R expression in NANOG/OCT4-HCC cell lines in a dose-dependent manner, suggesting crosstalk between IL-6/STAT3 signaling and IGF/IGF-1R signaling in HCC cancer stem cells." (PMID 33669204, 2021). "The IL-6/JAK/STAT3 pathway has a key role in the growth and development of many human cancers." (PMID 33725976, 2021). "In addition, Statins restrict tumor cell growth by inhibiting CCL3 secreted by cancer cells and IL-6 and CCL2 produced by MSC, thereby disrupting the communication between cancer cells and MSC." (PMID 34858839, 2021). "Among the many SASP factors, IL-6, CCL5, CXCL12, CCL2 and IL-8 have a particularly important role in supporting cancer cell metastasis formation and the establishment of an immunosuppressive microenvironment, although in some cancer models they can be found in the immune stimulatory secretome." (PMID 34079557, 2021). "However, aberrant IL-6 mediated STAT3 signalling has been reported to suppress anti-cancer immunity in HCC, making the STAT3 signalling a target in cancer treatment." (PMID 34078370, 2021). "In solid tumors, the evidence suggested that the paracrine effects of Il-6, IL-8, CXCR4, and IGF might endow cancer cells with the ability to counteract with cytotoxic effects of anticancer agents by up-regulating the expression of Bcl-2 and Bcl-xl." (PMID 35096289, 2021). "Given the relationship between ER stress, reactive oxygen species (ROS), and cancer, and the inflammatory signalling pathways mediated by NF-kB and IL-6, further work to explore the context-dependant contribution of TG2 in cancer progression would be informative." (PMID 34205140, 2021). "TAM-based IL-6 provokes not just immune cell penetration but also cancer stem cells (CSC) growth and sustenance." (PMID 34336101, 2021). "A careful look at the target molecules induced by ceramide, C1P, and S1P in inflammation and cancer reveals that they are rather related, if not the very same: for example, NFκB, TNFα, and IL‐6." (PMID 34289244, 2021).
cancer (continued). "Since soluble IL-6 is shed, among others, from neutrophils by ADAM10- and ADAM17-mediated proteolysis, inhibition of these proteolytic enzymes is expected to have a beneficial outcome in cancer." (PMID 34572138, 2021). "Accordingly, in addition to its own anti-cancer activities, pharmacological ERK1/2 inhibition may be a viable strategy to broadly decrease IL-6 production upon DNA damage, while retaining the anti-proliferative effects of the pathway, seen in MG-63 cells." (PMID 35087822, 2021). "On the other hand, in the BCG therapy response, the production of IL-4, IL-5, IL-6 and IL-10 by primary T helper 2 (TH2) was associated with BCG non-responsiveness and cancer progression." (PMID 33923108, 2021). "Cancer patients produce many inflammatory cytokines, such as tumor necrosis factor-alpha (TNF-α), proteolysis-inducing factor (PIF), interleukin-1 (IL-1), and interleukin-6 (IL-6)." (PMID 34724970, 2021). "Moreover, it is also well-known that IFN-γ acts as an important stimulus for skewing the Mφ phenotype into the M1 type, which exerts its anti-cancer efficacy through immune mediators, specifically iNOS, TNF, and IL-6." (PMID 34202080, 2021). "Further investigation into SASP components revealed that IL‐6 and IL‐8 are major drivers of SASP‐mediated EMT and invasiveness of premalignant or malignant cancer cells, given that their inhibition attenuates the migration into the basement membrane by cells stimulated by senescent CM." (PMID 32981205, 2021). "This association of PTGS2 with inflammatory cytokine expression extends to established cancer; analysis of mRNA-seq data from the Cancer Genome Atlas (TCGA) dataset showed positive correlations of PTGS2 expression with IL1B, IL6, IL8, and CXCL1 in all cancer types." (PMID 33730589, 2021). "Additionally, cancer and stromal cells produce various inflammatory cytokines, such as IL-1, IL-6, and IL-8, which in turn activate STAT3/NF-κB pathways in both cancer and stromal cells." (PMID 35006395, 2021). "In addition, IL-6 acts primarily through activating a series of downstream signaling cascades, including GP130, JAK/STAT, MAPK, and AKT, which are all involved in cancer initiation and progression." (PMID 34641563, 2021). "Lee and Beaty believed that general inflammation induced by IL6 was sufficient to establish an environment conducive to the spread of cancer cells in the liver, even in the absence of cancer." (PMID 35154607, 2021). "Moreover, silencing of PDS5B expression promotes cell proliferation via induction of IL-6 secretion and activation of STAT3, and promotion of cyclin D1 expression in human cancer." (PMID 34226509, 2021). "Another study with a mouse cancer model simulating the anatomical and functional features found in human oral cancer patients demonstrated that anti-NGF treatment decreased plasma TNF-α and IL-6 levels." (PMID 35053150, 2021). "If IL-6 is rightfully believed to be a biologically powerful player in cancer biology, here comes an inevitable question: Why has IL-6 not gained a similar position as a recognized biomarker (of any cancer type including HNSCC) so far?" (PMID 34681685, 2021). "Inflammation can be developed by a huge variety of diseases, including obesity, hyperglycemia, and excessive lipid accumulation, which can promote different types of cancers by releasing several factors such as ROS, TNF-α, IL-1, IL-6, IL-8, COX2, iNOS, and chemokines, among many others." (PMID 34202969, 2021). "The addition of 786O cancer cells led to an increase in MMP9, Gro-α, IL-8, IL-6, HB-EGF, and VEGF-A; and the addition of ccRCC PBMCs led to an increase in PDGF-BB and IL-1β as well as a further increase in MMP-9, Gro-α, IL-8, IL-6, and CCL-2 despite cabozantinib treatment." (PMID 34931665, 2021).
cancer (continued). "This includes inflammatory signals (e.g., IL-1, IL-6, and tumor necrosis factor (TNF)), TGF-β, physical changes in the ECM, contact signals with cancer cells, and DNA damage, resulting in a gain of proliferation, secretory phenotype, migration, and ECM production and remodeling." (PMID 33673405, 2021). "The relationship between stromal Rab37 and IL-6 expression has never been examined in TME of human cancer patients." (PMID 34093869, 2021). "By contrast, TLK2 and IL6 have not been reported as an amplification driver in either the Cancer Gene Census or OncoKB and they are amplified in 1–2% of the TCGA cohort." (PMID 34313788, 2021). "In nonmetastatic cancer patients, T cells were negatively correlated with IL-6 and IL-10 and were positively correlated with IL-4 and TNF-α." (PMID 34712741, 2021). "The established myokines IL6, irisin and SPARC have cancer-protective functions." (PMID 34359731, 2021). "Finally, CCL1 increases the expression of interleukin 6 (IL-6) in MDSC, which acts as a proinflammatory in the cancer microenvironment." (PMID 33076281, 2020). "It is known that IL6 and GDF15 serve as key mediators of cancer cachexia." (PMID 33182625, 2020). "Cancer cells can also produce IL-6 acting in an autocrine manner, in this way they do not depend on the paracrine release of IL-6 by stromal cells." (PMID 33260925, 2020). "Six months post-diagnosis, fatigue was assessed with the European Organization for Research and Treatment of Cancer quality of life questionnaire C30 (EORTC QLQ-C30), and in a subpopulation, the plasma levels of inflammation markers (IL6, IL8, TNFα, and hsCRP) were assessed." (PMID 33317113, 2020). "The IL-6 released from these macrophages, but not IL-10 and GM-CSF, suggests that cancer cells are promoting their proliferation in a paracrine manner." (PMID 32655574, 2020). "Epigenetic changes play an important role in the abnormal activation of the IL-6/IL-6R/JAK/STAT3 pathway in cancer, and changes in transcription factor expression and/or activation may be involved in cancer progression." (PMID 33363013, 2020). "Similar mechanisms were also found in the progression of NSCLC, where highly expressed plasminogen activator inhibitor 1 (PAI-1) enhances the expression of cytokines, including C-C motif chemokine ligand 17 (CCL17), CCL22, IL-6, and TGF-β1, in TAMs to promote cancer progression." (PMID 33114183, 2020). "Although these results show the importance of the activation of Gp130 and STAT signaling in cancer cachexia, Gp130 activation is not solely restricted to IL-6." (PMID 33329046, 2020). "Adiponectin could negatively regulate cancer cell growth via regulating inflammatory signaling molecules, including Erk1/2, Akt, tumor necrosis factor (TNF)-α, IL-1β, NF-κB, IL-6, IL-8 and CCL2." (PMID 32787888, 2020). "The Mantel–Haenszel test for heterogeneity was not significant except for cancer (hematologic and solid malignancies) with respect to D-dimer, and sex with respect to IL-6." (PMID 32677844, 2020). "Another study reported that TEV induced IL-6 release from MDSC and postulated that the role of TLR2 signaling could be dependent on the type of TEV-producing cancer cells." (PMID 32878277, 2020). "In addition, SCs were reported to secret a dramatically higher levels of IL6 and IL8 under hypoxia 18, all of which have been reported to promote cancer cell metastasis 19,20." (PMID 32308766, 2020). "IL6 has been shown to drive EMT, metastasis and therapy resistance in cancer." (PMID 32455670, 2020). "Furthermore, our group previously reported that CD5 in tumor infiltrating B cells binds to IL-6, and through gp130 induces STAT3 activation to promote cancer development." (PMID 33335857, 2020). "IL-6 was previously shown to be induced by PDT in vitro and in vivo but also in cancer patients." (PMID 32107566, 2020). "In patients with cancer, CRP levels are well known to correlate with IL-6 levels." (PMID 33291708, 2020).
cancer (continued). "In addition, TGF-β together with some chemokines and cytokines such as IL-6 and CXCL9 promote cancer progression by suppressing the antitumor immune response leading to the disruption of T cell function and cancer cell immune evasion." (PMID 33027902, 2020). "Basophils reportedly interact with and stimulate B cells through CD40L and release of IL-4, IL-6, IL-13, BAFF, and histamine, all of which may augment B cell proliferation, survival and antibody responses against cancer." (PMID 32645919, 2020). "Importantly, both MS4A1 and TIL-B levels are consistently prognostic across five cancer types, namely HNSCC, LUAD, CESC, LGG, and KIRP, with distinct Be2 and BK signatures (especially for IL2, IL6, and PD-L2 expressions)." (PMID 32398659, 2020). "Moreover, after receiving cancer treatment radioactivity in lung cells diminished and cancer promoting factors declined (VEGFR2, ICAM-1, bFGF, KC, TNF-α, IL-6, IL-12, IL-10 and IL-13) showing a diminution of metastatic competency of the exosomes." (PMID 32570802, 2020). "One case report in a patient with large-cell carcinoma of the lung and cancer cachexia demonstrated improved inflammatory outcomes with reduced serum IL-6 after prednisolone treatment, with no further deterioration in cachexia parameters." (PMID 33329046, 2020). "Moreover, TAM-derived chemokines/cytokines (e.g. TGF-β, IL-6, IL-10, and TNF-α) is shown to enhance stemness of cancer cells by promoting EMT." (PMID 32264958, 2020). "The systemic cellular response, as well as the systemic IL-6 in the animals of the Cancer and Saline groups did not demonstrate statistically significant differences." (PMID 32523654, 2020). "Interestingly, our results showed that IL-6 secreted by MSCs leads to STAT3 activation and upregulation of CD73 expression in cancer cells, promoting xenograft NPC growth and resistance to cisplatin treatment." (PMID 32127934, 2020). "Bone marrow-derived macrophage efferocytosis of apoptotic cancer cells, but not apoptotic normal cells, resulted in increased gene expression of Cxcl1, Cxcl4, Cxcl5, and IL-6 inflammatory cytokines in comparison with peritoneal macrophages." (PMID 32059476, 2020). "IL-6 is noteworthy owing that it has been broadly characterized as a major cancerogenic factor contributing to malignancy, EMT and metastasis of multifarious cancers, including HCC19." (PMID 31949128, 2020). "Lipolytic factors or hormones, such as tumor necrotic factor α (TNFα), interleukin-6 (IL-6), Zinc-α2-glycoprotein (ZAG), catecholamines, and natriuretic peptides, explain lipolysis in cancer cachexia." (PMID 32117967, 2020). "The results showed that there were 9 active components acting on key targets such as VEGFA, VWF, IL6, TNF, NFKB1, respectively, as well as regulating signaling pathways such as AGE-RAGE, FA, Toll-like receptor, PI3K/Akt, NF-κB, apoptosis and cancer signaling pathways." (PMID 33424592, 2020). "After metastasis, pro‐inflammatory cytokines, including Il1α, Il1β, Il6, Il18, and TNF‐α, were significantly induced in lung metastases, indicating that inflammatory cytokines may play a positive role in cancer metastasis." (PMID 34766117, 2020). "Indeed, proinflammatory cytokines such as IL-1, IL-6, and IFN-γ were described to lead to the expansion of MDSC in cancer and these cytokines are also elevated in the serum of diabetic patients as well as in healthy at-risk relatives without the disease onset." (PMID 33206686, 2020). "Besides IL-6, other cytokines such as type-I interferon, IL-1β, IL-7, IL-17, and TNF-α are central to the pathophysiology of COVID-1938 as well as to cancer pathogenesis and the therapeutic response." (PMID 32944387, 2020). "In addition, we also explored the role of IL6 in the stimulation of STAT3 and in the growth and proliferation of PTC cancer cells." (PMID 31936675, 2020). "The inflammatory cytokines such as IL-1, IL-6, TNF- α, and TGF-β could induce cancer cells proliferation and tumoral invasion through activation of NF-κB." (PMID 32458652, 2020).